CD4 (CD4 molecule)
Diseases named in the same sentence as CD4 in open-access papers (continued):
Sharing a sentence is not in itself a finding about the gene and the disease.
co-infection (continued). "Among the CD4 T cells in the ear dermis, it was possible to identify an increase in the percentage of IFN-γ+ cells in L. major-only infected mice, which was reduced following co-infection with P. berghei ANKA." (PMID 40720541, 2025). "In the CHIKV + P. berghei ANKA model, co-infection not only induces apoptosis of T cells in lymph nodes but also suppresses the production of chemoattractant factors such as MIP-1α and MIP-1β, thereby limiting the migration of CD4 T cells to joints." (PMID 40720541, 2025). "HIV coinfection did not significantly impact CD4 expression in coinfected patients post-DAA treatment." (PMID 41293057, 2025). "The heterogeneous results reported from studies assessing HIV coinfection as a factor determining serologic response could be due to differences in ART therapy, immunological status, and CD4 T-cell count." (PMID 40407643, 2025). "In our study, age, gender, HBV coinfection, CD4+ cell count, platelet count, and TNF-α were not correlated with the odds of death." (PMID 40006998, 2025). "Age advancement was not correlated with sex, current smoking, BMI, co‐infection with syphilis, CD4 nadir, or last CD4 counts." (PMID 39812213, 2025). "In contrast to the total CD4+ and CD8+ T‐cell findings in the spleen, IAV‐only infection significantly increased the infiltration of the number of effector CD8+ T cells in the spleen compared with both SFV and coinfection at 10 dpi." (PMID 39971320, 2025). "Detection of HTLV/HIV co-infection in patients solely infected with HIV is not consistently feasible; nonetheless, HIV patients with co-infections generally exhibit elevated CD4+ T-cell counts compared to those with mono-infection who progress to AIDS." (PMID 40284988, 2025). "Notably, the CD4 count was significantly lower in the HIV-infected only (629 ± 448 u/L) and HIV and helminth co-infection (579 ± 370 u/L) groups compared to the other groups, with a p-value of 0.001." (PMID 40143377, 2025). "Conversely, viremia was highest (significantly, p = 0.0273 compared to HLTBI− and p = 0.0357 compared to HLTBI+) in the HTB+ group, suggesting that co-infection with active TB favored HIV-1 viral replication and concomitantly increased pathology in terms of lowered CD4 counts and CD4/CD8 ratios." (PMID 41148837, 2025). "Lastly, adoptive transfer of human T cells in humanised mice led to recruitment of non-HBV/HDV-specific CD4+ T cells only in the setting of HBV/HDV coinfection, but not in HBV-mono-infected mice." (PMID 39980752, 2025). "The present study was done to assess the frequency of HIV-TB co-infection among the HIV positives in north India, to study the epidemiological and clinical factors related to the co-infections and the impact of TB infection on HIV disease progression in terms of CD4 counts." (PMID 40771827, 2025). "Furthermore, among the 102 cases with CD4 < 200 cells/μL, 62 (60.78%) had HIV/T. marneffei co-infection." (PMID 40892762, 2025). "Even in patients with HIV without co-infections, CD4+ remains low despite being under virological control, for example, immunological failure or immunological non-response." (PMID 38491526, 2024). "As the CD4+ T-cell count classification (low/high) for these patients largely overlapped with their HIV infection status, the observed effects of low CD4+ T-cell counts were largely similar to the effects of HIV co-infection." (PMID 38696531, 2024). "No LF differences at baseline in age, HIV coinfection course (CD4, HIV viral load), and HCV features (HCV viral load, genotype) were detected." (PMID 38553507, 2024). "Baseline CD4 cell count was significantly lower in participants with co-infection compared to those without co-infection." (PMID 38725704, 2024).
co-infection (continued). "To shed more light on the lymphocyte response in the context of HbTg co-infection, we investigated the changes in Th1 and Th2 cytokines at the systemic level, as well as IFN©-producing lymphocytes (NK, NKT, CD4+ T, CD8+ T and ©δ T cells) at day 5 and day 10 post-Tg infection in different organs." (PMID 38950025, 2024). "There was a reduction in CD4 T-lymphocytes, which in turn increased the number of neutrophils, CD8 T-lymphocytes and viral load, suggesting a state of greater and persistent systemic inflammation in individuals living with HIV/HPV coinfection." (PMID 39699423, 2024). "The present study shows that combining BLV and anti-HIV drugs did not affect HIV viral load or CD4 count in this population of adults living with HIV with HDV/HBV coinfection." (PMID 39045338, 2024). "Our results demonstrate that HpTg co-infection leads to a decrease in all IFN©−producing lymphocytes (CD8+ and CD4+ T as well as NK, NKT, ©δ T cells) in the MLN as a proportion and in absolute numbers, which helps explain the subsequent increase in Tg burden in this organ." (PMID 38950025, 2024). "Overall, we conclude that cART + 3HP fails to control immuneactivation post SIV co-infection of LTBI leading to exhaustion of CD4+ T cellsin pulmonary compartment." (PMID 39257997, 2024). "In this analysis from a large observational cohort, we found that being male, older age, HBV co-infection, HCV co-infection, lower CD4 + T cell and lower CD4/CD8 ratio at baseline were associated with immunological non-response." (PMID 38287246, 2024). "The effects of HIV co-infection might be complicated by ART, which alleviates the CD4+ T-cell depletion in HIV patients." (PMID 38696531, 2024). "Here, we demonstrate that KSHV/EBV co-infection of mice with reconstituted human immune systems (humanized mice) leads to IgM responses against both latent and lytic KSHV antigens, and expansion of central and effector memory CD4+ and CD8+ T cells." (PMID 38844783, 2024). "Candidate covariates tested included demographic (e.g., age, race, sex), HIV disease (e.g., HIV RNA in plasma, nadir and current CD4+ T cell counts), HIV treatment (e.g., ART use), and common comorbidities (e.g., neuropsychiatric comorbidities, HCV co-infection)." (PMID 38789639, 2024). "In our study, we also observed the highest prevalence of co-infection in the IDU cohort, which may have contributed to low CD4-cell counts." (PMID 39599831, 2024). "Alterations in CD8+ T cell populations during HIV/Mtb coinfection are less widely reported in non-blood samples relative to CD4+ T cells." (PMID 39204027, 2024). "However, having a CD4 count of ≤200 cells/mL serves as a proxy indicator for premature death during twine infection (during TB and HIV co-infection)." (PMID 39104893, 2024). "Compared with the HPV infection group, CT/HPV coinfection further downregulated the expression of MHC I and MHC II molecules on the LC surface and reduced the CD4+ and CD8+ CTL subsets, thus inhibiting cell-mediated immunity and leading to persistent HPV infection." (PMID 38378486, 2024). "A stringent analysis of the correlations of the cytokine levels with CD4+ cell counts did not reveal statistically significant differences between the two groups with HIV/TB co-infection (p values > 0.01)." (PMID 38790916, 2024). "This men-associated LF enhancing effect was also independent of the presence of HIV-coinfection, and of its course assessed by CD4 levels and HIV viral load." (PMID 38553507, 2024). "A longitudinal investigation of CD4+ T cell phenotypes of HIV-infected persons with or without TB co-infection will help dissect the specific mechanisms leading to different recovery status in these individuals." (PMID 38699317, 2024). "Our analysis revealed that children with lower CD4+ T cell count before treatment initiation did not experience immune recovery during the follow-up period, and the impact of TB co-infection on immunological recovery is minimal." (PMID 38699317, 2024).
co-infection (continued). "Both reactivators and those RM which do not reactivate Mtb following SIV co-infection experience comparable CD4 T cell depletion in the periphery as well as in the lungs and are characterized by the presence of comparable viral loads." (PMID 37764928, 2023). "The co-infection was higher among people aged ≥50 years (3.5%), with multiple sexual partners (4.0%), with no viral suppression (3.3%), with CD4 count <500 cells/mm3 (2.9%) and those who were HAART-naive (4.2%)." (PMID 37498806, 2023). "Our findings showed a high prevalence rate of co‐infection and their negative impact on CD4 + T cell counts of HIV‐infected patients." (PMID 36840494, 2023). "Additionally, during co-infection with PR8 and T. gondii (Pru), a decrease in CD4+ T cells led to a reduction in CD8+ T cell function, which prevented the T. gondii (Pru) infection from becoming chronic." (PMID 37235437, 2023). "The odds of HBV co-infection were higher among males, adolescents and syphilis positives, while syphilis co-infection was higher in patients with CD4 count <500 cells/mm3 and those who did not initiate HAART, p < .05." (PMID 37498806, 2023). "However, little is known about the prevalence of triple co‐infection of T. gondii, HBV, and HCV and their correlation with CD4 + T cell count among PLWH." (PMID 36840494, 2023). "Thus, in addition to the depletion and dysfunctionality of CD4 T cells, SIV co-infection induced chronic immune activation and aberrant signaling in Mtb-infected RMs, which together drove reactivation of TB." (PMID 37764928, 2023). "In particular, chronic immune activation rather than mere depletion of CD4+ T cells is the key correlate of reactivation due to SIV co-infection." (PMID 37764928, 2023). "Moreover, few studies reported clinical measure of HIV disease state (CD4 and viral load) to evaluate the impact of RHD co-infection on clinical HIV infection." (PMID 37720311, 2023). "In relation to helminth coinfection, based on the TB score, the intermediate and severe clinical classes of TB patients had a significantly lower frequency of IFN-γ+CD4+ T cells in PBMCs of helminth positive TB patients compared to helminth positive TB patients with SCI." (PMID 36662839, 2023). "However, little is known about co‐infection of these pathogens among HIV‐infected individuals and their correlation with the patient's CD4 + cell count." (PMID 36840494, 2023). "HIV infection causes steep reduction in CD4+ T cells, which negatively affects CD4+/CD8+ T cell balance, rendering the host inefficient in controlling secondary infections, which limits the options of designing vaccines to manage HIV–TB co-infection." (PMID 37243117, 2023). "Consistent with this, the analysis and comparison of granzyme A and perforin secretion of CD4+ T cells, CD8+ T cells and TCRαβ+ DNT cells also showed TCRαβ+ DNT cells might display cytotoxic T cells-like function in TB and HIV/TB co-infection." (PMID 36443691, 2022). "Further investigation of CD4+ T cell and CD68+ macrophage reconstitution within lung tissue was of interest as it is the site of initial infection for Mtb as well as co-localization during co-infection for HIV." (PMID 36146734, 2022). "The rates of CD4:CD8 normalization were also higher in the group of patients without HCV/HBV coinfection; however, rates of CD4 cells normalization were greater in the population of patients with coinfections." (PMID 36298842, 2022). "Surprisingly, CD4 counts did not increase in those with HPgV-1 co-infection whereas those without HPgV-1 had a rise of more than 1,000 CD4 cells/mm3, suggesting that HPgV-1 interferes with CD4 expansion and IL-2 signaling." (PMID 35707535, 2022). "The study showed that although CD4 cell counts were lower in patients with HIV/HBV co-infection than in patients with HIV mono-infection, there was no statistical difference between the two groups (P value = .307)." (PMID 36417469, 2022).
co-infection (continued). "This study aimed to compare RBC indices, anemia, and correlation of RBC indices and CD4 count in malaria-HIV co-infection as compared to HIV without malaria patients who were on HAART in Bench Sheko Zone." (PMID 35245289, 2022). "Similarly, the rapid initiation of ART in those diagnosed with HIV can help to maintain CD4+ T cells count at the optimum level, and this can help to bring down the HIV-HBV-HCV co-infection in them." (PMID 35239716, 2022). "Despite a large number of studies showing survival advantage, lower HIV VL, and higher CD4 in those with HIV and HPgV-1 coinfection, the interpretation of the Amsterdam data continues to reduce acceptance of the apparent beneficial effect of HPgV-1 on HIV survival." (PMID 35707535, 2022). "The presence of liver fibrosis over the study period was independently associated with plasma HIV RNA, CD4+T cell counts, HIV-HBV co-infection (for APRI >0.5) and ART non-adherence (for Fib-4 >1.45)." (PMID 35966860, 2022). "Thus, we defined the impact of HIV, TB, and HIV/aTB coinfection on the magnitude and phenotypical and functional profile of the SARS-CoV-2 CD4+ T cell response." (PMID 33945513, 2021). "For example co‐infection with HCV can increase the rate of decline of CD4 cells, and CD4 counts may vary between different geographic areas with faster CD4 decline observed in Asia compared to Europe." (PMID 33474833, 2021). "There are much evidences that recommend that patients with TB and HIV co-infection should receive therapy of both illnesses regardless of the CD4 cell count level." (PMID 34336428, 2021). "HIV disease outcomes following HAART (high active antiretroviral therapy) do not appear to be adversely affected by HBV or HCV co-infection, except for slightly poorer CD4 count responses in HIV/HCV co-infected patients." (PMID 34449737, 2021). "HIV disease outcomes following HAART do not appear to be adversely affected by HBV or HCV co-infection after 12 months, except for slightly poorer CD4 count responses in HIV/HCV co-infected patients." (PMID 34449737, 2021). "Thus, both human γ-herpesviruses invest some effort to compromise CD4+ T cell recognition, and CD4+ T cell depletion by antibodies or HIV co-infection decreases EBV-specific immune control in humanized mice." (PMID 34066671, 2021). "This is consistent with a recent study in Tanzania which reported mixed TH1/TH2 phenotypes in Mtb-specific CD4 T cells in individuals with active TB and helminth coinfection, although the participants in this study were not stratified by helminth species." (PMID 32117277, 2020). "Since IFN-γ is predominantly expressed by the CD4+ subset of T cells in TB patients, we hypothesized that HCV coinfection would affect the host immune markers on TB-specific CD4+ T cells." (PMID 31952232, 2020). "HIV viral load was higher in PF than in plasma of HIV-positive patients and was inversely correlated with the proportion of CD4+ T cells in PF28; thus, HIV co-infection was associated with false-negative results and the lower sensitivity of T-SPOT.TB16,17." (PMID 33004934, 2020). "Accordingly, poor adherence, lower CD4 count at baseline, age, TB/HIV co-infection, and non-disclosure status were associated with virological failure." (PMID 32611405, 2020). "This differs from studies of co-infection with filarial worms and soil-transmitted helminths, which have reported lower Mtb-specific TH1 cytokine production and lower frequencies of Mtb-specific TH1 cytokine+ CD4 T cells in LTBI individuals." (PMID 32117277, 2020). "Infections with a variety of helminths have been shown to dysregulate Mtb-specific CD4 T cell immunity, however a thorough analysis of CD4 T cell lineage commitment during co-infection with SM and Mtb in humans has not been conducted." (PMID 32117277, 2020). "Additionally, since HIV-1 and HTLV-1 infect the same cells (CD4 positive), the production of HIV-1 pseudotypes with HTLV-1 envelope glycoprotein during HIV/HTLV-1 coinfection cannot be excluded." (PMID 32999083, 2020).
co-infection (continued). "Together, these data indicate that Mtb-specific CD4 T cell inhibitory receptor expression profiles are significantly modified in the setting of HIV co-infection with active TB, but not LTBI." (PMID 31497018, 2019). "However, CD4+ T lymphocyte count (364 vs 512 vs 514 cells/μl; p = 0.0009) was significantly lower in HIV/HBV co-infection compared to HIV/HCV and HIV mono-infection respectively." (PMID 31323077, 2019). "Risk factors for lack of seroconversion include low CD4 T-cell count, high HIV viral load, HCV co-infection, and tobacco use." (PMID 30934708, 2019). "PCP with coinfections has been reported earlier with a significant increase in mortality rate, especially among children less than 5 years old and HIV-seropositive patients with CD4+ T-cell counts less than 200 cells/μl." (PMID 30718779, 2019). "ART should be initiated for all patients with TB/HIV co-infection regardless of their CD4 cell count." (PMID 31312318, 2019). "In conclusion, the present study provides evidence that M. tuberculosis-specific CD4 and CD8 T-cell responses are impacted by HIV coinfection, resulting in pronounced variations in the qualitative and quantitative profile of M. tuberculosis-specific T cells in human populations." (PMID 30541853, 2019). "In support of our study, it was also recently demonstrated that reactivation of LTBI in a macaque model of TB/SIV co-infection was independent of CD4+ T cells in at least one third of all animals." (PMID 30949177, 2019). "We retrospectively analyzed the clinical course and outcome of hemophilia A patients with HIV/HCV co-infection receiving DAA with a focus on the virological response, changes in cluster of differentiation 4 lymphocyte (CD4) count, side effects, and impact on bleeding before and after DAA therapy." (PMID 31348267, 2019). "As CD4+ T cells are the primary site for HIV-1 replication, the co-infection of the same cell could lead to a complex interaction between both viruses." (PMID 30944340, 2019). "We hypothesized that ART alters the clonotypic phenotype and structural composition of CD4+ and CD8+ T cells during CM co-infection." (PMID 31319498, 2019). "In the three models, female gender, no HCV-co-infection, as well as higher HIV-RNA, aCD4, CD4% or CD4/CD8 at baseline were associated with an increased probability of achieving the eIR." (PMID 30346965, 2018). "A multivariate logistic regression, including age, gender, HCV co‐infection, years of ART, change in CD4+ at WB since ART start (CD4+ slope), years of HIV‐RNA <50 copies/mL and months to ART start was performed to assess factors associated with a negative HIV‐1 pol." (PMID 30362663, 2018). "In accordance with previous studies, we found that female gender, no HCV-co-infection, and higher HIV-RNA, aCD4, CD4% or CD4/CD8 at baseline were consistently associated with an increased probability of reaching the target values of IR." (PMID 30346965, 2018). "We found that the patients who had co-infection by A. baumannii have fewer CD4+ and CD8+ T-cells, compared to H7N9 controls without co-infection, and also lower than the A. baumannii controls without H7N9 infection." (PMID 30551738, 2018). "As recommended in the WHO management guideline for HIV and TB co-infection, cART should be administered as soon as possible after the initiation of anti-TB treatment (within 8 weeks) without consideration of the CD4+ T cell count." (PMID 29587840, 2018). "Interestingly, co-infection reduced the numbers of total and CHIKV-specific CD4+ T cells in the pLN at 5 and 6 dpi." (PMID 30254309, 2018). "Another study from South Africa advocated that all patients with rifampicin-resistant TB–HIV co-infection should be initiated on ART regardless of CD4 count." (PMID 30080987, 2018). "For example, HIV-infected patients mostly suffer from co-infection with Mtb due to depletion of CD4+ T cells, whereas group 1 CD1-restricted T cells are not affected by HIV infection." (PMID 30538700, 2018).